TRAJ50 (T cell receptor alpha joining 50)
Gene: T-cell receptor joining (J) gene on chromosome 14 (22,488,593 to 22,488,652, forward strand). Ensembl gene ENSG00000211839.
Diseases named in the same sentence as TRAJ50 in open-access papers:
TRAJ50 is named in the same sentence as 1 disease in open-access papers, as found by Europe PMC text mining. Sharing a sentence is not in itself a finding about the gene and the disease.
TRAJ50 shares sentences with these, for which no sentence is quoted: COVID-19 (1 paper).